KRAS (KRas proto-oncogene, GTPase)
Diseases named in the same sentence as KRAS in open-access papers (continued):
Sharing a sentence is not in itself a finding about the gene and the disease.
ovarian carcinoma (272 papers, 1995 to 2026). A malignant neoplasm originating from the surface ovarian epithelium. "Ovarian cancer (OCa) remains the most lethal gynecologic malignancy in the United States, with low-grade serous and mucinous subtypes frequently driven by KRAS mutations." (PMID 41154625, 2025). "It determined the VAF of ovarian cancer‐related mutations KRAS‐G12R, NRAS‐G12C, and BRAF‐V600E in both tissue and blood samples (n = 77), discriminating cancer patients and healthy individuals with significant difference (p < 0.001)." (PMID 39903775, 2025). "While previous studies have identified genomic similarities between BOTs and other ovarian cancer types, including common mutations in KRAS and BRAF, the transcriptomic parallels we observed between BOTs and ECs represent a novel finding." (PMID 39840716, 2025). "At higher concentrations (>25 μM), DMF inhibits Nrf2, particularly in cancers with high Nrf2 activity (e.g., KRAS-mutated lung or ovarian cancers), by downregulating DJ-1, leading to increased oxidative stress and cytotoxicity." (PMID 41403438, 2025). "In a similar manner, an increase in the expression of GLS1 and ASCT2 was observed in ovarian cancer cells with a KRAS mutation." (PMID 40598593, 2025). "For instance, trametinib, a MEK inhibitor, has demonstrated efficacy in reducing tumor growth in KRAS-mutated ovarian cancer models." (PMID 40427025, 2025). "Among ovarian cancers, KRAS mutations are commonly detected as one of the most frequent abnormalities." (PMID 38627856, 2024). "In ovarian cancer, KRAS mutation was an increasing trend from normal ovaries to benign mucinous tumors, mucinous borderline tumors, and mucinous ovarian tumors." (PMID 38730733, 2024). "The meta-analysis unequivocally confirmed the existence of the KRAS mutation in epithelial ovarian cancer." (PMID 39492906, 2024). "Some of the molecular abnormalities encountered in endometriosis‐associated ovarian cancer include: the activation of oncogenic KRAS and PI3 K pathways and the inactivation of tumor suppressor genes PTEN and AT‐Rich Interaction Domain 1A (ARID1A)." (PMID 38962465, 2024). "The identification of the KRAS mutation in cfDNA has been advantageous in predicting the prognosis of individuals diagnosed with ovarian cancer." (PMID 39492906, 2024). "Patients with endometrial, lung and ovarian cancers also had a large frequency of variants in KRAS (11.0%, 11.8% and 10.8% respectively)." (PMID 39277826, 2024). "These patients included an ovarian cancer patient with KRAS G12D and EGFR G724S mutations with SD (- 9%) for 7 months and a salivary gland cancer patient with EGFR amplification by IHC with SD (+ 3%) for 5 months." (PMID 37314501, 2023). "PIK3CA and KRAS mutations in ctDNA serve as prognostic markers and indicate outcomes in epithelial ovarian cancer patients." (PMID 37629546, 2023). "The MMR germline carriers with endometrial cancer had more somatic MMR variants, while those with ovarian cancer harbored more common variants in driver genes, including KRAS, ARID1A, and PTEN." (PMID 37523182, 2023). "The AL/CDDP-nanogel showed high in vivo efficacy when delivered intraperitoneally against an ovarian cancer mouse model using ovarian cancer cell lines with KRAS mutations (ID8-KRAS: KRASG12V)." (PMID 38112935, 2023). "Through exome sequencing, it was observed that 79% of the lesions (EC and/or DIE) had mutations, and 26% of these were found in the ARID1A, PIK3CA, KRAS, and PPP2R1A genes, where PIK3CA and KRAS are genes frequently mutated in ovarian cancer." (PMID 35807280, 2022). "KRAS mutations have different specificities depending on tumor type, with KRAS G12V mutations most commonly found in ovarian cancer, while the least common in cholangiocarcinoma." (PMID 36686734, 2022).
ovarian carcinoma (continued). "In fact, the effect on growth suppression of MAPK pathway inhibition in ovarian carcinoma cells was more profound in tumors harboring KRAS mutation than in KRAS wild-type tumors." (PMID 35204416, 2022). "In preclinical data on ovarian cancer, cell lines with KRAS or BRAF mutations experienced significant growth inhibition and apoptosis compared to wild-type cells." (PMID 35204549, 2022). "The genomic amplification of KRAS, in particular, is associated with metastatic disease and poor prognosis in hormone-related cancers such as ovarian cancer." (PMID 35216221, 2022). "Preliminary evidence of clinical activity was observed with gedatolisib uniting PD-0325901 in patients with ovarian cancer (three partial responses) or endometrial cancer (one partial response) with KRAS mutations." (PMID 33593355, 2021). "The meta-analysis clarified the presence of KRAS mutation in epithelial ovarian cancer, and the KRAS mutation in cfDNA was associated not only with poor OS but also with poor PFS." (PMID 33936202, 2021). "KRAS, mutations in which cause ovarian carcinoma, has a z-score of -0.12 in ovary and FUGUE score of 0.82." (PMID 34270548, 2021). "So, the detection of KRAS mutation in cfDNA was beneficial to the prognosis of ovarian cancer patients." (PMID 33936202, 2021). "A direct comparison of these immune probes in high-risk and low-risk classifications revealed that KRAS signaling upregulation (| log fold change| = 0.297, adjusted P-value < 0.0001) was the top enriched signature in high-risk ovarian cancer." (PMID 34386037, 2021). "The presence of mutations in KRAS and the effects of KRAS pathway alteration remain an open point of discussion under investigation in clinical trials of ovarian cancer patients." (PMID 33671478, 2021). "In a recent study, GDC-0941 and siRNA therapeutics targeting KRAS (siKRAS) have been combined to test their synergistic anti-tumor effect in ovarian cancer cell lines and in an allograft ovarian cancer model harboring KRAS mutations." (PMID 34946644, 2021). "In a phase I clinical study of a rare ovarian cancer subtype, Spreafico reported that favorable objective responses were obtained by simultaneous inhibition of MEK and PI3K in patients with KRAS mutation-associated ovarian cancer." (PMID 34885229, 2021). "Perhaps the tumor is a mix of high and low-grade serous cancer (since the primary KRAS mutations are characteristic of low-grade ovarian carcinoma)." (PMID 32766142, 2020). "When we compared the mutation of ovarian cancer to other mucin-producing tumors, they all have the same mutant genes which were KRAS and BRAF, but different in the percentage of mutation." (PMID 31030485, 2019). "All four cases that had the PIK3CA mutation were in stage IA of ovarian cancer and all of them also had the KRAS mutation." (PMID 31030485, 2019). "Type I ovarian cancer, which includes low‐grade serous carcinoma, endometrioid carcinoma, clear cell carcinoma, and mucinous carcinoma, has been shown to exhibit KRAS, BRAF, PI3KCA, and PTEN mutations." (PMID 29797793, 2018). "The contributions of both ARID1A and KRAS warrant further study in terms of endometriosis, the endometriotic tumor microenvironment, and endometriosis-associated ovarian cancer." (PMID 30087267, 2018). "The KRAS variant found in one tumor (c.35G > T) has previously been reported as a somatic variant in ovarian cancer (COSM520)." (PMID 28611940, 2017). "The coexistence of PIK3CA and KRAS mutations has been shown in several different tumors types including lung, colorectal, pancreatic and ovarian cancer." (PMID 26968814, 2016). "We herein demonstrated that c-MYC and KRAS accelerated the production of ovarian cancer-associated ascites." (PMID 27483433, 2016).
ovarian carcinoma (continued). "For ovarian cancer, KRAS is the most frequently mutated gene (18%), whereas PIK3CA is mostly affected in cervical cancer (24%) and PTEN in endometrial cancer (39%)." (PMID 24671188, 2014). "A previous study has shown that the MAPK pathways have a significant role in the development and differentiation of ovarian cancer caused by KRAS and BRAF mutations." (PMID 25202426, 2014). "We previously reported the KRAS mutation profiles of type II ovarian carcinoma cell lines; these data were used for subsequent in vitro analysis." (PMID 23820584, 2013). "In the current study, type II ovarian carcinomas with both KRAS mutations and KRAS amplification were highly sensitive to growth inhibition by the selective MEK inhibitor, PD0325901." (PMID 23820584, 2013). "Here, we investigated the occurrence, clinicopathological correlates and prognostic significance of specific KRAS mutations in tumours from 153 epithelial ovarian cancer (EOC) cases from a pooled, prospective cohort." (PMID 23800114, 2013). "No previous studies have evaluated the effect of panitumumab in ovarian cancer (OC) based on KRAS mutation status." (PMID 23577259, 2013). "We reported earlier that KRAS or BRAF mutations were quite common in low-grade serous ovarian carcinomas with prototypic histology of type I ovarian carcinoma but rare in high-grade serous ovarian carcinomas." (PMID 23820584, 2013). "In this pooled prospective cohort of epithelial ovarian cancer, significant associations were found between KRAS mutations and mucinous histology, well differentiated tumours and positive progesterone expression." (PMID 23800114, 2013). "In fact, other mechanisms have been suggested in other types of tumors, as CHD5 mutation or methylation is associated with KRAS or BRAF mutation in ovarian cancer, and CHD5 expression correlates with MYCN amplification in neuroblastoma." (PMID 22569290, 2012). "The KRAS-variant is significantly associated with the risk of developing additional cancers beyond breast and ovarian cancer." (PMID 22662244, 2012). "The KRAS-variant is significantly more likely to be found in women tested within two years of their ovarian cancer diagnosis." (PMID 22662244, 2012). "This association with older age of ovarian cancer onset in KRAS-variant-positive uninformative patients was significant by logistic regression analysis (p<0.007)." (PMID 22662244, 2012). "Our findings here indicate that women with the KRAS-variant are also at an increased risk of subsequently developing ovarian cancer, and should be managed accordingly." (PMID 22662244, 2012). "Somatic mutations in the oncogenes KRAS or BRAF usually occur as mutually exclusive events in epithelial ovarian cancer, have been reported in borderline ovarian serous carcinomas or low-grade ovarian serous carcinomas, and occur at a low frequency in HGSCs." (PMID 23029043, 2012). "The KRAS-variant is significantly associated with developing ovarian cancer post-menopausally compared to pre-menopausally." (PMID 22662244, 2012). "Overall, the KRAS-variant was found in 21.0% of the entire cohort of double primary breast and ovarian cancer patients with full clinical information (n = 42/200)." (PMID 22662244, 2012). "Such disparities in these and other areas of study cohort and design likely explain the failure to find the association between the KRAS-variant and sporadic ovarian cancer risk in a prior publication." (PMID 22662244, 2012). "The goal of this study was to determine the association of the KRAS-variant with women with double primary breast and ovarian cancer, to further validate the association of this variant with HBOC families." (PMID 22662244, 2012).
ovarian carcinoma (continued). "In ovarian cancer, mutations most often affect codons 12 and 13 of the KRAS gene, with mutation rates reported to be as high as 3–11%." (PMID 19358724, 2009). "In summary, KRAS mutation is a common event in ovarian cancer and is more frequently present in carcinoma of lower grade, lower FIGO stage, and in lesions of mucinous histotype." (PMID 19358724, 2009). "As of late KRAS mutations in ovarian cancer should stand in the center of attention again due to the availability of EGFR-targeted therapies (e.g. Gefitinib, Erlotinib, and Cetuximab), that are already in use to treat patients with NSCLC and metastatic CRC." (PMID 19358724, 2009). "As KRAS mutations are associated with poor response and resistance to EGFR-targeting drugs, this study was conducted to obtain more information on the spectrum of KRAS mutations in ovarian carcinoma." (PMID 19358724, 2009). "KRAS mutation is a common event in ovarian cancer primarily in carcinomas of lower grade, lower FIGO stage, and mucinous histotype." (PMID 19358724, 2009). "In ovarian cancer, KRAS mutation has been identified in 35% low-grade serous tumors and 33% of borderline tumors, whereas, BRAF mutations occur in 30% of low-grade serous carcinomas and 28% of borderline tumors." (PMID 19638206, 2009). "Next, to clarify the roles of ERK1/2 activation in ovarian cancers harbouring KRAS or BRAF mutations, we inactivated ERK1/2 in ovarian cancer cells using CI-1040." (PMID 19018267, 2008). "A panel of ovarian cancer cell lines and primary cultures was first analysed for tumour mutation status in the KRAS and BRAF genes." (PMID 19018267, 2008). "A panel of ovarian cancer cell lines and primary cultures of ovarian cancer were first analysed for KRAS and BRAF gene mutation status." (PMID 19018267, 2008). "The findings in this study indicate that an activated ERK1/2 pathway is critical to tumour growth and survival of ovarian cancers with KRAS or BRAF mutations." (PMID 19018267, 2008). "This study examined the status of KRAS and BRAF mutations, in relation to extracellular signal-regulated protein kinase (ERK) activation in 58 ovarian carcinomas to clarify the clinicopathological and prognostic significance of KRAS/BRAF mutations." (PMID 19018267, 2008). "Somatic mutations of either KRAS or BRAF were identified in 12 (20.6%) out of 58 ovarian carcinomas." (PMID 19018267, 2008). "In summary, we have shown that the phenotypic change in ovarian carcinomas in response to ERK1/2 inactivation depends on the mutational status of KRAS and BRAF." (PMID 19018267, 2008). "Ovarian carcinomas with mutations in either KRAS or BRAF were more sensitive to growth inhibition and apoptosis induction by the MEK inhibitor, CI-1040." (PMID 19018267, 2008). "Ovarian carcinomas with KRAS or BRAF mutation are clinically low-grade carcinomas of serous or other histological subtypes that are often refractory to conventional cytotoxic chemotherapy." (PMID 19018267, 2008). "Profound growth inhibition and apoptosis were observed in CI-1040-treated cancer cells with mutations in either KRAS or BRAF in comparison with the ovarian cancer cells containing wild-type sequences." (PMID 19018267, 2008). "In light of our in vivo and in vitro findings, we propose that ovarian cancer patients with KRAS or BRAF mutations be considered for MEK inhibitor (CI-1040) therapy if they recur after conventional platinum and taxane chemotherapy." (PMID 19018267, 2008).
ovarian carcinoma (continued). "Moreover, the gene KRAS, known to be mutated in endometriosis-associated ovarian cancer (EAOC), shows clustering with the gene ADAMTS19, which is known to promote proliferation and invasion in EAOC cells." (PMID 41516028, 2025). "However, when ovarian cancer cells were segregated based on their KRAS or PI3K (includes PIK3CA and PTEN mutations) mutational status, FK866-sensitivity (IC50) was more comparable to the most sensitive cell types (highly sensitive blood cancers)." (PMID 41419662, 2025). "Similarly, in KRAS/NRAS mutated type I epithelial ovarian cancers, including MOCs, the MEK inhibitor treatment resulted in tumor shrinkage, durable responses, and a CA125-related response." (PMID 40862711, 2025). "The results indicated that serum KRAS exhibits a diagnostic accuracy in distinguishing between early and late stage of ovarian cancer (AUC = 0.8, 95% CI = 0.682 to 0.949, P = 0.0002), demonstrating a sensitivity of 87.86% and specificity of 80% at a cutoff > 149.7 ng/ml." (PMID 40913040, 2025). "Mucinous ovarian carcinoma (MOC) represents a rare and biologically distinct subtype of ovarian cancer, characterized by poor response to standard platinum-based chemotherapy and a unique molecular profile, including frequent KRAS mutations and HER2 amplifications." (PMID 40862711, 2025). "Additionally, the KRAS mutation is considerably more common in MOCs compared to other ovarian cancer types." (PMID 40862711, 2025). "However, the KRAS mutation associated with the PTEN loss-of-function mutation developed an endometrioid type of ovarian cancer in preclinical models." (PMID 38646168, 2024). "Interestingly, both patients with SD ≥ 4 months harbored EGFR aberrations, including an ovarian cancer patient with KRAS G12D and EGFR G724S mutations and a salivary gland cancer patient with EGFR amplification by IHC." (PMID 37314501, 2023). "KRAS was identified as a commonly mutated oncogene in different subtypes of ovarian cancer." (PMID 37110218, 2023). "Mutated KRAS were involved in the development of ovarian cancer." (PMID 37110218, 2023). "Additionally, SNU8, an ovarian cancer cell line with the KRAS V12 mutation, exhibited similar trends in mRNA expression following trametinib treatment." (PMID 37779141, 2023). "The results show that ovarian cancer in the high-risk group may be involved in epithelial-mesenchymal transition, KRAS signaling pathway, TNF NFKB signaling pathway, and angiogenesis, while the low-risk group is negatively associated with E2F and MYC pathways." (PMID 37859811, 2023). "The KRAS gene is mutated in 14% of ovarian cancers, commonly in codon G12 (41%, COSMIC)." (PMID 36609632, 2023). "Similarly, the presence of a KRAS-variant has also been suggested as a biomarker of poor outcome in epithelial ovarian cancer likely due to platinum resistance." (PMID 36612212, 2022). "Clinicopathologically, a dualistic model of ovarian cancer has been proposed: Type I tumors, comprised of low-grade serous, low-grade endometrioid, mucinous, and clear cell carcinomas, typically possess mutations in KRAS, PTEN, and CTNNB1." (PMID 35159108, 2022). "Gunal reported that hsa-let-7d-3p could downregulate the HMGA2 and KRAS genes and that the loss of hsa-let-7d-3p expression led to the progression of epithelial ovarian cancer related to tumorigenesis, invasion, and metastasis." (PMID 35907902, 2022). "A putative regulatory axis of let-7d, HMGA2 and KRAS may be associated with tumorigenesis, invasion, and metastasis in epithelial ovarian cancer." (PMID 34298978, 2021).